TRAF4 (TNF receptor associated factor 4)
Diseases named in the same sentence as TRAF4 in open-access papers (continued):
Sharing a sentence is not in itself a finding about the gene and the disease.
ovarian carcinoma (6 papers, 2018 to 2025). A malignant neoplasm originating from the surface ovarian epithelium. "The expression of SRC-3 and TRAF4 in ovarian cancer cells was downregulated by transient transfection with sh-RNAs." (PMID 36625999, 2023). "This study aimed to explore the role of the SRC-3/TRAF4/PI3K/AKT pathway in ovarian cancer development." (PMID 36625999, 2023). "A better understanding of the molecular mechanisms of the SRC-3/TRAF4 axis in the development of ovarian cancer will improve our understanding of carcinogenesis and facilitate additional therapeutic avenues for targeting ovarian cancers." (PMID 36625999, 2023). "Our study demonstrated that SRC-3/TRAF4 promotes ovarian cancer cell growth, migration, invasion, and stemness by activating the PI3K/AKT pathway." (PMID 36625999, 2023). "Taken together, these results strongly support that SRC-3 and TRAF4 are upregulated in ovarian cancer cells." (PMID 36625999, 2023). "Collectively, our study demonstrates the involvement of SRC-3/TRAF4 pathway in ovarian cancer development." (PMID 36625999, 2023). "SRC-3 and TRAF4 expression in ovarian cancer cell lines were assessed using qRT-PCR and western-blotting." (PMID 36625999, 2023). "In this study, we tested the growth, migration, invasion, and stemness of ovarian cancer cells by knocking down expression of SRC-3 or TRAF4." (PMID 36625999, 2023). "In our study, the TRAF4/PI3K/AKT pathway was found to be involved in ovarian cancer development." (PMID 36625999, 2023). "SRC-3 and TRAF4 were upregulated in ovarian cancer cell lines." (PMID 36625999, 2023). "We further investigated the role of the SRC-3/TRAF4/PI3K/AKT pathway in ovarian cancer development." (PMID 36625999, 2023). "However, to our knowledge, this is the first study to show that SRC-3 activates the TRAF4/PI3K/AKT pathway to promote ovarian cancer development." (PMID 36625999, 2023). "We assessed the mRNA levels of SRC-3 and TRAF4 in multiple ovarian cancer cell lines using qRT-PCR." (PMID 36625999, 2023). "In addition, we verified that the specific binding of SRC-3 and TRAF4 in ovarian cancer cells promoted the development of ovarian cancer by activating the PI3K/AKT pathway." (PMID 36625999, 2023). "However, it is unclear whether SRC-3 employs a similar TRAF4/PI3K/AKT pathway to facilitate ovarian cancer development." (PMID 36625999, 2023). "In agreement with previous studies, our results showed that overexpression of TRAF4 neutralized the effect of SRC-3 knockdown and rescued ovarian cancer cell migration and invasion." (PMID 36625999, 2023). "Overall, our results suggest that SRC-3/TRAF4 activates the PI3K/AKT signaling pathway and plays an important role in the growth, migration, invasion, and stemness of ovarian cancer cells." (PMID 36625999, 2023). "In conclusion, our study demonstrates that reducing the expression of TRAF4, TRAF5, or TRAF6 significantly improves the sensitivity of human ovarian cancer or melanoma cells to retinoic acid." (PMID 37389738, 2023). "We also found that TRAF4 and KIF11 were upregulated in ovarian carcinomas and that their level of expression was positively correlated with that of DR6." (PMID 30186750, 2018). "Because SRC-3 and TRAF4 were more highly expressed in CAOV-3 and SKOV3 cells than in other ovarian cancer cell lines, we speculated that these two cell lines might be most significantly regulated by the expression of SRC3 and TRAF4." (PMID 36625999, 2023). "The mRNA levels of SRC-3 and TRAF4 were increased in ovarian cancer cell lines, such as Anglne, CAOV-3, IGROV1, SW626, and SKOV3, compared to normal ovarian epithelial cells, IOSE80, with the mRNA levels of SRC3 and TRAF4 in CAOV3 and SKOV3 cells showing the highest change." (PMID 36625999, 2023).
ovarian carcinoma (continued). "In this study, we found that TRAF4, TRAF5, and TRAF6 were upregulated in several TCGA cancer cohorts and cancer cell lines, especially in ovarian cancer and melanoma cell lines, indicating their potential correlation with retinoic acid sensitivity in these cells." (PMID 37389738, 2023). "Additionally, inhibiting TRAF4, TRAF5, or TRAF6 improved retinoic acid sensitivity and reduced colony formation in ovarian cancer and melanoma cells." (PMID 37389738, 2023). "As the SRC-3/TRAF4/PI3K/AKT pathway plays a vital role in ovarian cancer development, the SRC-3/TRAF4 pathway may be a promising therapeutic target for ovarian cancer treatment." (PMID 36625999, 2023). "Our results suggested that suppressing TRAF4, TRAF5, or TRAF6 can decrease the proliferation of ovarian cancer and melanoma cells and improve the sensitivity of these cells to retinoic acid treatment, probably by regulating cell apoptosis-related signaling pathways." (PMID 37389738, 2023). "Targeting TRAF4, TRAF5, or TRAF6 could be a promising strategy for inhibiting ovarian cancer and melanoma cell proliferation." (PMID 37389738, 2023). "The findings above suggest that DR6 may play a notable oncogenic role in ovarian malignancy by interacting with TRAF4 and KIF11, and that DR6 may be an effective therapeutic target in ovarian cancer." (PMID 30186750, 2018). "Furthermore, sh-TRAF4 as well as treatment with LY294002, the PI3K/Akt inhibitor, inhibited the phosphorylation of Akt and PI3K, thus repressing the activation of PI3K/AKT signaling pathway in ovarian cancer cell lines." (PMID 36625999, 2023). "TRAF4 and TRAF6, noncanonical members of the TRAF family, are widely recognized as oncogenes in various human malignancies, including lung cancer, breast cancer, ovarian cancer, melanomas, neurogenic tumors, colon cancer, osteosarcoma, and pancreatic cancer." (PMID 37389738, 2023).
Obesity (5 papers, 2016 to 2024). Accumulation of substantial excess body fat. "Curcumin, a natural phenolic compound that shows an anti-obesity effect, has been reported to reduce the expression of ALKHB5 and then increase the translation of TNF receptor-associated factor 4 (TRAF4) by up-regulating its mRNA m6A modification level." (PMID 38560499, 2024). "Curcumin reduces the production of ALKB homolog 5 (ALKHB5), which can enhance the expression of mA-modified TNF receptor-associated factor 4 (TRAF4) mRNA, and so decreases HFD-mediated obesity." (PMID 37110167, 2023). "Mechanistically, m6A-dependent TNF receptor-associated factor 4 (TRAF4) expression upregulation by AlkB homolog 5 (ALKHB5) and YTH-domain family 1 (YTHDF1), which thus promoted PPAR-γ degradation by the ubiquitin-proteasome system, contributed to CUR-induced obesity prevention." (PMID 36233207, 2022). "Our findings suggest that miR-4443 acts in a tumor-suppressive manner by down-regulating TRAF4 and NCOA1 downstream of MEK-C/EBP-mediated leptin and insulin signaling, and that insulin and/or leptin resistance (e.g. in obesity) may suppress this pathway and increase the risk of metastatic CRC." (PMID 27842582, 2016).
breast tumor (4 papers, 2022 to 2025). "The expression of TRAF4 is positively correlated with SRC-3 expression in breast tumors." (PMID 36625999, 2023). "As a downstream factor of SRC-3, the protein level of TRAF4 is regulated by SRC-3 in cells and breast tumors." (PMID 36625999, 2023). "Wogonside inhibits breast tumor growth and metastasis by suppressing TRAF2 and TRAF4 expression in situ models of MDA-MB-231 cells." (PMID 35242717, 2022).
endometrial cancer (4 papers, 2022 to 2025). Primary or metastatic malignant neoplasm involving the endometrium (mucous membrane that lines the endometrial cavity). "The TRAF4/PI3K/AKT/Oct4 pathway regulates the progression of endometrial cancer by promoting cell proliferation and migration." (PMID 36625999, 2023). "Previous studies have reported that TRAF4 activates the PI3K/AKT pathway to promote endometrial cancer development." (PMID 36625999, 2023). "TRAF4 promotes the development of endometrial cancer by activating the PI3K/AKT pathway and enhancing the phosphorylation of AKT and PI3K." (PMID 36625999, 2023). "The effect of TRAF4 on the sensitivity of endometrial cancer EC cells to oncologic agents such as olaparib was mainly mediated by AKT phosphorylation mediated." (PMID 35242717, 2022). "TRAF4 increased the expression of Oct4 in endometrial cancer cells." (PMID 36625999, 2023). "A previous study reported that TRAF4 was upregulated in endometrial cancer tissues." (PMID 36625999, 2023). "TRAF4 promotes cell proliferation and migration by activating the PI3K/AKT/Oct4 pathway, which regulates the progression of endometrial cancer." (PMID 36625999, 2023).
esophageal squamous cell carcinoma (4 papers, 2019 to 2020). Esophageal squamous cell carcinoma (ESCC) is a type of esophageal carcinoma (EC) that can affect any part of the esophagus, but is usually located in the upper or middle third. "miR-21-3p promotes proliferation and anti-apoptosis in esophageal squamous cell carcinoma (ESCC) by regulating tnf receptor associated factor 4 (TRAF4)." (PMID 32595638, 2020). "Collectively, we identified surface biomarkers of stem cells in esophageal squamous cell carcinoma, and discovered thathsa-miR-21-3p may be involved in stemness maintenance by regulating TRAF4." (PMID 30979011, 2019).
intrahepatic cholangiocarcinoma (3 papers, 2020 to 2023). A carcinoma that arises from the intrahepatic bile duct epithelium in any site of the intrahepatic biliary tree. "High levels of TRAF4 promote intrahepatic cholangiocarcinoma (ICC) cell invasiveness by activating AKT signaling, and TRAF4 overexpression is associated with shorter overall survival and higher recurrence rates in ICC patients." (PMID 35242717, 2022).
non-small cell lung carcinoma (3 papers, 2020 to 2022). A group of at least three distinct histological types of lung cancer, including non-small cell squamous cell carcinoma, adenocarcinoma, and large cell carcinoma. "This miRNA can further downregulate oncogenic TRAF4 to inhibit non-small-cell lung cancer (NSCLC) progression." (PMID 35356749, 2022).
osteoporosis (3 papers, 2019 to 2024). A condition of reduced bone mass, with decreased cortical thickness and a decrease in the number and size of the trabeculae of cancellous bone (but normal chemical composition), resulting in increased fracture incidence. "TRAF4 is markedly reduced in bone sections of ovariectomized rats with local osteoporosis and patients with osteoporosis." (PMID 38940355, 2024). "Taken together, these results indicated that the expression of TRAF4–Smurf2 axis in the osteoblast lineage was abnormal in osteoporosis." (PMID 31076633, 2019). "Furthermore, TRAF4 was abnormally decreased in bone sections of ovariectomized rat and osteoporosis patients." (PMID 31076633, 2019). "Next, we examined whether the expression of TRAF4 was impaired in osteoblasts during osteoporosis in bone sections using immunofluorescence staining." (PMID 31076633, 2019). "Thus, our finding of an abnormal decrease in TRAF4 in osteoporosis indicated that TRAF4 may play an important role in the pathogenesis of bone metabolism disorders, such as osteoporosis." (PMID 31076633, 2019).
autoimmune disease (2 papers, 2011 to 2017). A disorder resulting from loss of function or tissue destruction of an organ or multiple organs, arising from humoral or cellular immune responses of the individual to their own tissue constituents. "Additional Ets1 target genes include ones important for immune function such as Il5ra, Tlr1, Traf4, and Ltk, but that not yet been implicated as susceptibility loci for autoimmune disease." (PMID 28439269, 2017). "However, TRAF4-deficient mice have not been challenged for bacterial resistance or autoimmune diseases and a role for TRAF4 in these processes cannot be ruled out." (PMID 24212830, 2011).
cholangiocarcinoma (2 papers, 2020 to 2024). A carcinoma that arises from the intrahepatic biliary tree (intrahepatic cholangiocarcinoma) or from the junction, or adjacent to the junction, of the right and left hepatic ducts (hilar cholangiocarcinoma). "It has been reported that the upregulated TRAF4 was present in cholangiocarcinoma." (PMID 33817231, 2020).
colitis (2 papers, 2013 to 2025). Inflammation of the colon. "Thus, it is possible that TRAF4 acts as a key upstream regulator of CAV1 expression in colitis; however, definitive confirmation necessitates additional experimental evidence." (PMID 40877233, 2025). "Given that segmental changes can exhibit inflammation in the colon in IBD patients and that intestinal segments in endoscopic remission can appear as histologic colitis, we determined the expressions of TRAF4 and TRAF6 both in inflamed and non-inflamed intestinal mucosae." (PMID 23431243, 2013).
Crohn disease (2 papers, 2016 to 2024). A gastrointestinal disorder characterized by chronic inflammation involving all layers of the intestinal wall, noncaseating granulomas affecting the intestinal wall and regional lymph nodes, and transmural fibrosis. "Our data support the identification of the increased TRAF4 expression in airway inflammation, Crohn disease and indicate the need for further studies." (PMID 27086366, 2016). "Except the high differences in the expression of TRAF4 between control and neoplastic cells, the differences in inflammatory diseases like Crohn disease or airway inflammation were described." (PMID 27086366, 2016).
inflammatory bowel disease (2 papers, 2013 to 2017). A spectrum of small and large bowel inflammatory diseases of unknown etiology. "A study demonstrated that two members of the TRAF family, TRAF4 and TRAF-6, were activated in patients with inflammatory bowel disease (IBD) and that both TRAF4 and TRAF-6 showed potential diagnostic value in differential diagnosis." (PMID 28219358, 2017). "Although it has been found that TRAF4 and TRAF6 share the same TRAF binding sites, comprehensive study of TRAF4 and TRAF6 in inflammatory bowel disease (IBD) is still lacking." (PMID 23431243, 2013).
small cell lung carcinoma (2 papers, 2020 to 2022). Small cell lung cancer (SCLC) is a highly aggressive malignant neoplasm, accounting for 10-15% of lung cancer cases, characterized byrapid growth, and early metastasis. "TRAF4 is a target gene for miR- in small cell lung cancer (SCLC)." (PMID 35242717, 2022).
squamous cell carcinoma (2 papers, 2019). A carcinoma arising from squamous epithelial cells. "TRAF4, through its interaction with the adaptor protein Act1, was implicated in an intriguing pathway involving skin biology and tumor formation in squamous cell carcinoma (SCC)." (PMID 31316496, 2019). "Evidently, despite the role of TRAF4 in propagating and promoting IL-17-Act1 MEKK3-ERK5 pathway and its implication in squamous cell carcinoma, TRAF4 is also involved in negative regulation of the IL-17 cascade." (PMID 31316496, 2019).
viral infection (2 papers, 2022 to 2025). "It is thus speculated that TRAF4 functions in response to bacterial and viral infections in teleosts." (PMID 35898509, 2022).
allergic asthma (1 paper, 2023). A asthma with a basis in a pathological type I hypersensitivity reaction. "Previous studies showed that TRAF4 is an important regulator of type 2 responses in murine allergic asthma models." (PMID 37607012, 2023).
Alzheimer disease (1 paper, 2021). A progressive, neurodegenerative disease characterized by loss of function and death of nerve cells in several areas of the brain leading to loss of cognitive function such as memory and language. "Expression of TNF Receptor Associated Factor similar to TRAF4 was observed in mouse Models of Down's Syndrome and Alzheimer’s disease." (PMID 34182925, 2021).
anaphylaxis (1 paper, 2025). An acute hypersensitivity reaction that occurs from exposure to an allergen. "ISM patients with insect venom–induced anaphylaxis show distinct gene expression profiles compared to those without such reactions, while significant expression of TRAF4 is linked to food hypersensitivity and reduced B3GAT1 expression is associated with insect venom‐triggered anaphylaxis." (PMID 41031827, 2025).
Ataxia (1 paper, 2012). Ataxia refers to impaired coordination of voluntary muscle movement. "Behavorial analyses show that TRAF4-deficient mice (TRAF4-KO) exhibit altered locomotion coordination typical of ataxia." (PMID 22363515, 2012). "Collectively, all these symptoms indicate that TRAF4 deficiency induces an alteration in locomotion coordination typical of ataxia." (PMID 22363515, 2012). "Since it has been reported that myelin disorganization leads to alterations in locomotion coordination and/or severe ataxia, CNS myelin organization was examined in WT and TRAF4-KO mice." (PMID 22363515, 2012). "The locomotion/motor coordination deficits observed in TRAF4-KO mice are similar to that described for several spontaneous murine mutants exhibiting cerebellar ataxia." (PMID 22363515, 2012). "The ataxia observed in the TRAF4-KO mice may therefore be due to modifications in the cerebellum microcircuitry." (PMID 22363515, 2012). "Here we show that TRAF4-KO mice exhibit altered coordination of locomotion, typical of ataxia." (PMID 22363515, 2012).
atherosclerosis (1 paper, 2022). A disease characterized by the build-up of fatty material and calcium deposition in the arterial wall resulting in partial or complete occlusion of the arterial lumen. "There is only spare information about the role of TRAF4 in atherosclerosis due to the limited viability of TRAF4−/− mice." (PMID 35252400, 2022). "Evidence that TRAF4 is directly involved in vascular inflammation and atherosclerosis is missing." (PMID 35252400, 2022).
bone metabolism disorders (1 paper, 2019). "Further studying TRAF4 may provide novel insight for understanding pathogenesis of bone metabolism disorders and reveal new therapeutic targets." (PMID 31076633, 2019).
colon adenocarcinoma (1 paper, 2023). "The mRNA levels of TRAF4 and Bcl-xL were upregulated in colon adenocarcinoma (COAD) and rectum adenocarcinoma (READ), and exhibited a positive correlation in CRC." (PMID 36765039, 2023).
cystic kidney disease (1 paper, 2012). A congenital or acquired kidney disorder characterized by the presence of renal cysts. "Analyses indicated 13 genes, in addition to Nek8 and Ift20 within this area that could potentially result in cystic kidney disease, namely: RGD1309077Phf12, Flot2, Spag5, Sdf2, Supt6h, Proca1, Traf4, Sarm1, Nlk and Ksr1." (PMID 22899815, 2012).
diabetes (1 paper, 2020). "The effect of CPP extract on various genes such as Pdx-1, Ins-1, ngn-3, GLUT-4, and IRS-1 in insulin signaling pathway and Traf-4, Traf-6, and Mapk-8 in MAPK downstream JNK cascade was examined through qRT-PCR to access the core molecular mechanism involved in CPP-induced recovery of diabetes." (PMID 32256963, 2020).
experimental autoimmune encephalomyelitis (1 paper, 2017). An autoimmune demyelinating disease of the central nervous system that is produced experimentally in animals by the injection of homogenized brain or spinal cord in Freund's adjuvant. "In experimental autoimmune encephalomyelitis model, the TRAF4-deficient mice had increased numbers of immune cell infiltration in the brain and a significantly higher expression of proinflammatory genes compared with that in the control mice." (PMID 29163513, 2017).